NLRP3 (NLR family pyrin domain containing 3)
Diseases named in the same sentence as NLRP3 in open-access papers (continued):
Sharing a sentence is not in itself a finding about the gene and the disease.
atherosclerosis (continued). "Indeed, increased NLRP3 activation is associated with several age-related pathological conditions, including Alzheimer’s disease, atherosclerosis and type-2 diabetes, whereas NLRP3 inhibition extends health-spans and diminishes age-dependent degenerative conditions." (PMID 37049611, 2023). "Furthermore, studies using bone marrow-transplanted mice, lentivirus-mediated NLRP3 gene silencing or the selective NLRP3 inhibitor MCC950 in apoE−/− mice have provided direct evidence that the NLRP3 inflammasome contributes to the progression of atherosclerosis." (PMID 37109221, 2023). "Therefore, UA might influence the development and progression of atherosclerosis through activating NLRP3 inflammasome." (PMID 36627567, 2023). "Moreover, NF-κB/NLRP3 pathway contributes to the macrophage pyroptosis in atherosclerosis." (PMID 36229750, 2023). "Thus, targeting NLRP3 inflammasome signaling might be a novel interventional therapy to attenuate atherosclerosis." (PMID 37123477, 2023). "Apart from their role in diabetes mellitus control or in all spectrum heart failure, sodium–glucose cotransporter-2 inhibitors (SGLT2i) may play a role in the atherosclerosis reversal on a mice model by the inhibitory effect on IL-1β through ROS/NLRP3/caspase-1 signaling." (PMID 37600028, 2023). "Normal activation of the NLRP3 inflammasome contributes to host defense, but abnormal activation is pathogenic in inherited disorders such as cryopyrin-associated periodic syndrome (CAPS) and complex diseases such as multiple sclerosis, type 2 diabetes, Alzheimer’s disease, and atherosclerosis." (PMID 36677800, 2023). "Because the NLRP3 inflammasome sequelae are critical to the development ofatherosclerosis by orchestrating the expression of inflammatory cytokines, it islikely that direct inhibition of inflammatory pathways through the NLRP3inflammasome would be a promising therapy for atherosclerosis." (PMID 39077721, 2022). "Thispromotes the development of atherosclerosis by exacerbating inflammation.Nonetheless, the NLRP3 inflammasome can also trigger apoptosis byactivating caspase-8 in macrophages, although it remains unknown whether thisfunction hinders the development of atherosclerosis." (PMID 39076616, 2022). "The ability of colchicine to interfere with the activation of the NLRP3 inflammasome, in addition to its effect on microtubule formation and neutrophil-mediated inflammation, points towards the use of colchicine as a potential strategy to target the inflammatory component of atherosclerosis." (PMID 35890291, 2022). "However, there are limited data on whether aerobic exercise modulates FGF21 to inhibit pyroptosis mediated by NLRP3 inflammasome and then prevent atherosclerosis." (PMID 36006939, 2022). "Moving downstream in the NLRP3 inflammasome pathway, IL-1 is a major mediator of inflammation in various pathologic states, such as autoinflammatory diseases (familial Mediterranean fever), acute infections, and chronic inflammatory environments, such as cancer and atherosclerosis." (PMID 36555579, 2022). "Additionally, NLRP3-dependent pyroptosis mediates endothelial dysfunction, which provides an impetus for hypertension, cardiovascular complications of coronary heart disease, and atherosclerosis in endothelial cells." (PMID 36187801, 2022). "In vivo and in vitro experiments have demonstrated that IL-36α promotes the NLRP3 expression and activation in mouse renal tubular epithelial cells and macrophages, while IL-36Ra inhibits NLRP3 activation and reduces inflammation in a mouse model of atherosclerosis." (PMID 35903102, 2022). "NLRP3 inflammasome is a valuable constituent with both prognostic and therapeutic value and its targeting could be the basis for new therapeutic classes in the treatment of atherosclerosis." (PMID 35563387, 2022).
atherosclerosis (continued). "Therefore, based on the main action of NLRP3 inflammasome in the stage of atherosclerosis, it could be suggested that the anakinra dose and the effect on each cell line are different as presented in this study." (PMID 35563294, 2022). "Taken together, these studies suggest that NLRP3-dependent pyroptosis in macrophages and foam cells may promote the formation of necrotic core formation and the instability of plaque, and further contribute to the progression of atherosclerosis." (PMID 36304814, 2022). "Therefore, inhibition of NLRP3 dependent caspase-1 production may alleviate the development of atherosclerosis." (PMID 35844498, 2022). "Moreover, in a mouse model of age-related clonal haematopoiesis of indeterminate potential (CHIP), detrimental phenotypes of increased clonality and atherosclerosis, together with the overexpression of NLRP3 and IL-1β, were largely prevented by the use of an NLRP3 inhibitor." (PMID 35159168, 2022). "In the absence of infection or disease, NLRP3 activity is tightly regulated, whilst dysregulated activation is strongly associated with chronic inflammatory diseases, including atherosclerosis and neurodegeneration." (PMID 35755447, 2022). "Therefore, this study explores the mediator's role of pyroptosis between NLRP3 inflammasome and atherosclerosis, which may shed light on the molecular mechanism and therapeutic potential in the origination and progression of atherosclerosis." (PMID 36304814, 2022). "Therefore, IL-1β has been considered as a key mediator of NLRP3 inflammasome and atherosclerosis." (PMID 36304814, 2022). "However, virtually nothing is known regarding whether the NLRP3 inflammasome dictates vascular inflammation and atherosclerosis through regulating autophagy and efferocytosis, a process by which apoptotic cells in tissues are engulfed by phagocytes." (PMID 35641492, 2022). "NLRP3, caspase-1, and apoptosis associated speck-like protein (ASC) are the key components of the NLRP3 inflammasome, which have been found to be highly expressed in plaques of the aorta and carotid arteries, as well as the subcutaneous fat of patients with atherosclerosis." (PMID 36082127, 2022). "Moreover, mtROS/mtDNA can also trigger NLRP3 inflammasome in atherosclerosis." (PMID 36304814, 2022). "In addition, SCFAs may be leveraged as an emerging therapy for atherosclerosis via regulation of NLRP3 inflammasome activity." (PMID 36082127, 2022). "In addition to the lipid-lowering effects, statins also possess anti-inflammatory effects, and it was reported that the inhibitory effects of statins on TLR4/NF-κB and NLRP3 inflammasome pathways contributed to the treatment of atherosclerosis and other inflammation-driven diseases." (PMID 35078487, 2022). "The DENRGs were particularly involved in necroptosis, lipids and atherosclerosis, TNF signaling pathway, legionellosis, cytosolic DNA-sensing pathway, RIPK1-mediated regulated necrosis, TRAIL signaling, Kaposi sarcoma-associated herpesvirus infection, and the NLRP3 inflammasome." (PMID 35991562, 2022). "Additionally, atheroprone flow induces the nod-like receptor protein-3 (NLRP3) inflammasome in the endothelium through SREBP2, and the activated NLRP3 inflammasome synergizes with hyperlipidemia to increase atherosclerosis in apolipoprotein E-/- (ApoE-/-) mice." (PMID 34094640, 2021). "As one of the most important multimeric protein complexes, NLRP3 inflammasome activation leads to increased cleavage of caspase-1 and downstream IL-1β production, and plays a pathological role in many diseases including diabetes, atherosclerosis and cardiovascular diseases." (PMID 34583676, 2021).
atherosclerosis (continued). "Although the role of these factors in atherosclerosis needs to be verified by further in vivo work, these discoveries have one thing in common that atherosclerosis-related ECs pyroptosis is achieved through the assembly of NLRP3 inflammasome and the activation of caspase-1." (PMID 34122076, 2021). "Meanwhile, significant inhibition of nicotine-accelerated atherosclerotic plaque formation was shown in mice fed with MβCD, suggesting α1-nAchR/lipid raft-mediated NLRP3 inflammasome signal may be the potential mechanism for the activation of macrophage and the progression of atherosclerosis." (PMID 34490270, 2021). "Importantly, nicotine-induced NLRP3 inflammasome activation and macrophage migration into atherosclerotic plaque were reversed by methyl-β-cyclodextrin, making a significant improvement for atherosclerosis in apoE–/– mice fed with a high-fat diet." (PMID 34490270, 2021). "The role of NLRP3 activation pathways in the development of different cardiovascular disorders has been widely characterized, given their potential contribution to the development of diseases such as atherosclerosis, myocardial infarction (MI), and other cardiomyopathies." (PMID 33923537, 2021). "Numerous studies have indicated that excessive NLRP3 inflammasome activation is harmful to the host immune system and can lead to many diseases that are related to the long-term inflammatory process including type 2 diabetes mellitus, atherosclerosis, rheumatoid arthritis, and gout." (PMID 35095532, 2021). "Interestingly, NLRP3 inflammasome activation, which leads to inflammatory cytokine release and pyroptosis, has been shown to be involved in immune-related diseases, such as rheumatoid arthritis (RA), type 2 diabetes, atherosclerosis, and asthma." (PMID 34630429, 2021). "Activation of NLRP3 inflammasome and IL-1 cytokines such as IL-1β and IL-18 were shown to be critically involved in the ensuing post-infarct systemic inflammation and progression of atherosclerosis through contributing to the initiation, formation, growth, and rupture of atherosclerotic plaques." (PMID 33804661, 2021). "Extracellular NLRP3 inflammasome particles are internalized into human coronary artery smooth muscle cells where they induce pro-inflammatory and pro-atherogenic effects representing a novel mechanism of cell-cell communication and perpetuation of inflammation in atherosclerosis." (PMID 34312415, 2021). "Interestingly, whilst NLRP3 deficiency in ApoE KO mice does not reverse atherosclerosis progression, NLRP3 mediates systemic inflammation and pathogenesis in LDL receptor KO mice that are fed a western diet." (PMID 32883606, 2020). "Consequently, MCC950/CRID3‐mediated inhibition of NLRP3 has shown beneficial effects in mice and other preclinical species that have been subjected to disease models, among which models of atherosclerosis, myocardial infarction, colitis, and skin and airway inflammation." (PMID 32770571, 2020). "Therefore, inhibiting the NLRP3 inflammasome is a potential approach for atherosclerosis therapy." (PMID 31993073, 2020). "In addition, high expression of CD147, an alternative receptor, and activation of the NLRP3 inflammasome may also contribute to atherosclerosis in the context of COVID-19." (PMID 33553222, 2020). "As the NLRP3 inflammasome recognizes and responses to the board range medicinally relevant stimuli, dysregulated NLRP3 inflammasome activation participates many human inflammatory diseases, including gout, type II diabetes, atherosclerosis and neurodegenerative disorders." (PMID 31979265, 2020). "In addition, some inflammatory factors, such as IL-1 and NLRP3, can also affect atherosclerosis." (PMID 32733941, 2020). "Therefore, the NLRP3 inflammasome might be the key regulator accounting for the protective effects of fucoidan on atherosclerosis." (PMID 33505579, 2020).
atherosclerosis (continued). "Several reports suggest that deregulated activation of NLRP3 inflammasome is involved in arthritis, diabetes, and chronic diseases such as metabolic syndrome, atherosclerosis, and other age-related diseases, and that its altered activity might increase the susceptibility to psoriasis." (PMID 33585499, 2020). "NLRP3 activation and proinflammatory cytokine secretion may promote atherosclerosis." (PMID 31408958, 2019). "Glibenclamide inhibits the activation of NLRP3 inflammasome and protects against inflammation and tissue damage in many inflammatory diseases, including bronchopulmonary dysplasia, allergic asthma, acute pancreatitis (York, Castellanos, Cabay, & Fantuzzi, 2014), sepsis, and atherosclerosis." (PMID 30859754, 2019). "The NLRP3 inflammasome, a multiprotein complex including NLRP3, caspase-1, IL-1β and ASC, has been widely shown to be an essential step in cardiovascular disease and is linked to atrial fibrillation, atherosclerosis, diabetic cardiomyopathy and cardiac remodeling." (PMID 31354519, 2019). "Moreover, NLRP3 inflammasomes show high expression in the aorta of patients with atherosclerosis." (PMID 31582899, 2019). "NLRP3 pathway inhibition could indeed effectively target inflammatory pathways in atherosclerosis." (PMID 31312638, 2019). "NLRP3 might also facilitate atherosclerosis via sensing oxidative mtDNA." (PMID 30405440, 2018). "Although the NLRP3 inflammasome is important in innate immunity to fight infection, excessive activation of this complex is involved in a variety of common diseases, including gout, atherosclerosis, type 2 diabetes, neurodegenerative diseases, and cardiovascular disorders." (PMID 30186288, 2018). "Moreover, silence of NLRP3 gene has been found to delay the progression of atherosclerosis in mice." (PMID 28104929, 2016). "In addition, we evaluated the potential relationship between HNF1A rs1183910, LEPR rs4420065, GCKR rs1260326, NLRP3 rs12239046, IL1F10 rs6734238, PPP1R3B rs9987289, ASCL1 rs10745954, HNF4A rs1800961 and SALL1 rs10521222 polymorphisms and CV events or subclinical atherosclerosis in RA patients." (PMID 27534721, 2016). "Moreover, mRNA levels of ABCA1 and ABCG1 were increased after the treatment of NLRP3i, suggesting that NLRP3 gene silencing could be a potentially therapeutic mean to increase macrophage cholesterol efflux for the prevention of atherosclerosis." (PMID 27239478, 2016). "In the development of atherosclerosis, cholesterol may activate the NLRP3 inflammasome in two ways." (PMID 25761252, 2015). "It was shown that NLRP3 may play a role in vascular lipid deposition and atherosclerosis." (PMID 26273672, 2015). "Thus, in addition to cholesterol crystals, there may be other endogenous substances activating the NLRP3 inflammasome in patients with atherosclerosis, such as oxidized low-density lipoprotein (oxLDL)." (PMID 25761252, 2015). "The third cluster (blue, 124 items) centers on inflammation-related pathways and specific pathological conditions, incorporating both molecular mediators (Nrf2, NLRP3, HMGB1) and disease states (atherosclerosis, ulcerative colitis, liver diseases)." (PMID 40242756, 2025). "Aberrant NLRP3 inflammasome activation contributes to diverse inflammatory disorders, including sepsis, CAPS, peritonitis, atherosclerosis, and experimental autoimmune encephalomyelitis (EAE), underscoring its therapeutic relevance." (PMID 41231359, 2025). "Moreover, as a ROS-related protein, ITGB2 could interact with multiple genes (e.g., HIF-1α) to promote ROS production, NLRP3 inflammasome activation, pyroptosis, and foam cell formation in macrophages, suggesting its potential role in the progression of atherosclerosis." (PMID 41348730, 2025).
atherosclerosis (continued). "Ox-LDL, a critical lipid component in atherosclerosis, induces ROS production, which oxidizes GSDMD and activates the NLRP3 inflammasome." (PMID 40244103, 2025). "In advanced atherosclerosis stages, prostaglandin endoperoxide synthase 2 (PTGS2), ACSL4, caspase-1, and NOD-like receptor protein 3 (NLRP3) expression is upregulated, while GPX4 is downregulated." (PMID 40308274, 2025). "For example, in a mouse model of atherosclerosis induced by a HFD, the protein levels of NLRP3, ASC, GSDMD-N, IL-1β, and IL-18 were significantly elevated; GSDMD-mediated pyroptosis then accelerated the progression of atherosclerosis." (PMID 41194915, 2025). "Research indicates that activation of the NLRP3 inflammasome is critical in CVD, particularly concerning atherosclerosis and MI." (PMID 41194915, 2025). "In atherosclerosis, gut microbial imbalance promotes the generation of pro-inflammatory bile acids (e.g., DCA, CDCA), reinforcing vascular inflammation through NLRP3 activation and lipid accumulation in macrophages." (PMID 41480102, 2025). "These advantages make nitroxoline a promising therapeutic option for NLRP3-related diseases such as gout, CAPS syndrome, and potentially atherosclerosis." (PMID 40835597, 2025). "The NLRP3 inflammasome is instrumental in the pathogenesis of CVD, particularly in conditions such as atherosclerosis, ischemia/reperfusion (I/R) injury, and HF." (PMID 41194915, 2025). "In a porcine model of T2DM and atherosclerosis, increased expression of sterol regulatory element-binding protein (SREBP)-1 in the aorta correlated with elevated NLRP3 inflammasome components." (PMID 40648980, 2025). "Recent studies have highlighted hsCRP’s role in activating the NLRP3 inflammasome in endothelial cells, linking it to LDL transcytosis and atherosclerosis progression through reactive oxygen species (ROS) regulation and inflammasome activation." (PMID 39941486, 2025). "Taken together, these results suggest that vulnerable psEVs promote endothelial inflammation and atherosclerosis partially through miR‐497‐5p delivery and UCP2 suppression to modulate the ROS/TXNIP/NLRP3 pathway." (PMID 40391195, 2025). "Knockout of NLRP3, ASC, and IL-1α/β significantly mitigated early atherosclerosis and IL-18 levels when subjected to a Western-style high-cholesterol diet." (PMID 41194915, 2025). "Recent studies have demonstrated that CD36 triggers the NLRP3 inflammasome in atherosclerosis, while inhibition of CD36 suppresses NLRP3 inflammasome activation." (PMID 38572426, 2024). "In the vivo atherosclerosis model, repeated administration of METTL3 shRNA prevented the atherogenic process and the upregulation of NLRP3." (PMID 39227813, 2024). "In the present study, we revealed that LSS-mediated IKKε phosphorylation promoted the expression of NLRP3 via activating the downstream transcription factor STAT1, leading to endothelial cell pyroptosis and atherosclerosis." (PMID 38315275, 2024). "Our findings indicate that the progression of early atherosclerosis and NETosis is promoted by a distinct pathway involving ER cholesterol accumulation, CaMKII/JNK activation, and BRCC3-mediated deubiquitylation of NLRP3." (PMID 38522750, 2024). "Reduced lanosterol levels in mice transgenically overexpressing 3β-hydroxysterol Δ24-reductase (DHCR24), further correlated with progression of atherosclerosis, as well as with enhanced type I IFN responses and NLRP3-dependent inflammasome activation." (PMID 36744258, 2023). "Mechanistically, the major triggers for NLRP3 inflammasome are oxidized LDL (oxLDL), cholesterol crystals and calcium phosphate crystals in atherosclerosis." (PMID 37336361, 2023). "In a study about the role of Long non-coding RNA MDRL in atherosclerosis, a close relationship is presented between miR-361-5p and MDRL, which is involved in the NLRP3 inflammasome activation and apoptosis in VSMCs during atherogenesis." (PMID 37328892, 2023).